PPARG (peroxisome proliferator activated receptor gamma)
Diseases named in the same sentence as PPARG in open-access papers (continued):
Sharing a sentence is not in itself a finding about the gene and the disease.
mastitis (11 papers, 2017 to 2026). Inflammation of breast tissue during lactation or postpartum due to an obstructed duct or infection. "Collectively, these data indicate that EPA attenuates mastitis-associated inflammation at least in part through the PPARγ-NF-κB axis." (PMID 42072713, 2026). "Moreover, in mice with LPS-induced mastitis, besides the suppression of LPS-induced NF-κB activation, activating peroxisome proliferator-activated receptor gamma (PPAR-γ) was regarded as another underlying anti-inflammatory mechanism of melatonin." (PMID 28387721, 2017). "Additionally, Se deficiency during Staphylococcus aureus-induced mastitis exacerbated the proinflammatory cytokine response due to suppressed PPARγ activity, and increased NF-κB activation, that resulted in increased nitric oxide levels and larger inflammatory lesions." (PMID 34777335, 2021). "In conclusion, Rg1 is proven to alleviate BMB disruption by activating PPARγ to inhibit oxidative stress and subsequent excessive autophagy in the case of subclinical bovine mastitis." (PMID 39765775, 2024). "Based on Western blotting in the present research, the mammary glands with subclinical bovine mastitis exhibited obviously increased PPARα expressions but reduced PPARδ/β and PPARγ expressions, in contrast to the healthy mammary glands." (PMID 39765775, 2024). "In vitro works suggest that ruminants peroxisome proliferator-activated receptor gamma (PPARγ) can aid in improving the response to mastitis and can control milk fat synthesis." (PMID 28740504, 2017). "For the purpose of clarifying whether Rg1 recovers TJs to alleviate BMB disruption by activating PPARγ while restraining oxidative stress in organisms, a typical mouse model of mastitis induced by LTA was established." (PMID 39765775, 2024). "The PPARγ may also play a role in tissue regeneration after mastitis because in monogastrics all PPAR isotypes play an important role in wound reepithelialization." (PMID 28740504, 2017). "Furthermore, it has been documented that Se could enhance the expression of IL10, peroxisome-proliferator-activated receptor gamma (PPAR-γ) activity and suppress NF-κB and nitric oxide in the mammary gland of mice caused by S. aureus-induced mastitis." (PMID 35453342, 2022). "In an LPS-induced mastitis model, EPA restored the LPS-reduced PPARγ protein level and suppressed NF-κB p65 activation, consistent with reduced nuclear translocation of p65." (PMID 42072713, 2026). "Therefore, the present study hypothesized that activation of PPARγ by 2,4-TZD in goats supplemented with adequate amounts of vitamin A can improve the response to sub-clinical mastitis." (PMID 31195666, 2019).
colorectal tumor (10 papers, 2006 to 2024). "Furthermore, TTI-101 treatment also led to the upregulation of important genes such as GUCA2A, CDX2, VDR, GSTM1, HPGD, and PPARG that have been shown by others to be associated with the prevention of large intestine neoplasms." (PMID 37296943, 2023). "were associated with prevention/protection against large intestine neoplasms, including GUCA2A, CDX2, VDR, VEFGA, GSTM1, HPGD, and PPARG." (PMID 37296943, 2023). "In our study, real time RT-PCR analysis demonstrates a significant enhancement in the expression of PPARγ in colorectal tumours as compared to normal surrounding mucosa." (PMID 16854216, 2006). "Little is know about the relationship between polyamine metabolism and PPARγ expression in colorectal tumours and available information is derived from in vitro studies." (PMID 16854216, 2006). "In colorectal tumour tissue, we observed an increase in PPARγ and SSAT expression as well as in SSAT activity." (PMID 16854216, 2006). "Furthermore, PPARG has been described as a colorectal tumour suppressor with anti-inflammatory and immunomodulatory capacities, in concordance with our TNMplot and Kaplan–Meier curve results." (PMID 36835258, 2023). "Studies performed with colorectal tumour cell lines have shown that cells transfected with the PPARγ restored the SSAT promoter activity, and an activated PPARγ could increase SSAT expression in these cells." (PMID 16854216, 2006). "In addition, colorectal tumor is developed by the activation of PPARγ." (PMID 32709256, 2020). "In a recent study an increase of PPARγ expression in comparison to normal mucosa it has been observed in 25% (four) of patients with colorectal tumour These contrasting results could be attributed to differences in methodological procedures as well as to the number of patients analyzed." (PMID 16854216, 2006). "In cancer biology PPARγ is the most intensively studied PPAR isoform and several studies have shown the protective role of this nuclear receptor in colorectal tumour." (PMID 16854216, 2006).
dilated cardiomyopathy (10 papers, 2012 to 2024). Cardiomyopathy which is characterized by dilation and contractile dysfunction of the left and right ventricles. "Cardiomyocyte-specific overexpression of PPARγ causes dilated cardiomyopathy associated with lipotoxicity in mice." (PMID 39596228, 2024). "Heart-specific PPARγ overexpression induced a dilated cardiomyopathy associated with increased expression of FAO genes, lipotoxicity, and mitochondrial structural abnormalities such as cristae disruption in the heart." (PMID 30400386, 2018). "It has been shown that overexpression of PPARγ in mice created a dilated cardiomyopathy associated with increased lipid stores and altered mitochondrial architecture." (PMID 29576853, 2018). "However, several recent studies have indicated that tissue-specific loss of PPARγ alters heart function and that cardiac over expression of PPARγ leads to a dilated cardiomyopathy associated with increased lipid and glycogen stores." (PMID 22563432, 2012). "In contrast, treatment with PPAR-γ agonists improved heart function in rodent models of lipotoxic dilated cardiomyopathy with unclear mechanisms, since rosiglitazone treatment of wild-type mice reduced expression of PPARγ targets." (PMID 34006325, 2021). "For example, overexpression of LpL or PPARγ in hearts induced lipotoxic cardiomyopathy phenotypes including ectopic cardiac lipid accumulation and dilated cardiomyopathy." (PMID 30485307, 2018). "On one hand, overexpression of PPARγ in transgenic mice was reported to evoke accumulation of lipids and glycogen and distortion of mitochondrial architecture leading to dilated cardiomyopathy." (PMID 29093735, 2017). "In contrast, murine cardiac PPARγ overexpression leads to dilated cardiomyopathy, accumulation of TG and increased free FA uptake." (PMID 25559887, 2015). "Another study demonstrated that transgenic mice with enhanced PPARγ activity developed concentric hypertrophy which progressed to dilated cardiomyopathy." (PMID 24938300, 2014).
hyperhomocysteinemia (10 papers, 2010 to 2024). A serious metabolic condition caused by mutations in the MTHFR gene, medications, or nutritional deficiency. "In summary, our study revealed metabolic disturbances in this model of long-term hyperhomocysteinemia together with vascular remodeling and suggested that impaired oxidative stress, endothelium dysfunction, and decreased PPARγ expression in the vessel wall could be underlying mechanisms." (PMID 29552030, 2018). "Here, we reported that pharmacological activation of peroxisome proliferator-activated receptor gamma (PPARγ) by TXL improves endothelial function in rats with hyperhomocysteinemia." (PMID 26539238, 2015). "Several studies also suggested that increased activity of PPARG could lower plasma Hcy, while hyperhomocysteinemia has been found to reduce the protein expression of PPARG." (PMID 35356087, 2022). "In addition, hyperhomocysteinemia reduced the expression of anti-inflammatory genes, i.e., PPARγ and PPARα in human monocytes." (PMID 34771080, 2021). "Our study may suggest a potential benefit of PPARγ agonists on reversing the Hcy-mediated vascular remodeling in patients with hyperhomocysteinemia." (PMID 29552030, 2018).
hyperuricemia (10 papers, 2019 to 2026). An abnormally high level of uric acid. "This study identified vitexin as one of the primary active flavonoids in hawthorn that ameliorate hyperuricemia by targeting the PPARγ/ABCG2 pathway." (PMID 42255677, 2026). "For instance, miR-199a-5p was reported to inhibit endoplasmic reticulum stress in renal ischemia-reperfusion (I/R) injury and to down-regulate PPARγ, exacerbating renal interstitial fibrosis in rats with hyperuricemia." (PMID 37958504, 2023). "Additionally, PPARγ activation plays a protective role against hyperuricemia-induced inflammatory response and decreases the expression of proinflammatory cytokines and chemokines." (PMID 34938805, 2021). "Further, hyperuricemia may downregulate the expression of adiponectin via attenuating peroxisome proliferator-activated receptor gamma (PPARγ) in adipocytes." (PMID 34588926, 2021). "In the mouse with hyperuricemia, the expression of ATP-binding cassette subfamily G member 2 in ileum was activated by acetylation PGC-1α/PPARγ pathway after SIRT1 activation by Res, reducing the level of serum uric acid, thus exerting an anti-hyperuricemia effect." (PMID 36632457, 2023).
osteonecrosis (10 papers, 2012 to 2025). A none disease characterized by death of bone tissue due to a lack of blood supply. "Our previous research also identified an association between gene variants of the transcription factor PPARγ and the development of osteonecrosis of the femoral head in the Chinese population." (PMID 40259926, 2025). "Several studies have also reported the abnormal expression and related regulatory effects of PPARγ in osteonecrosis of the femoral head." (PMID 40259926, 2025). "It was indicated that inhibition of PPARγ probably represents a novel therapy for steroid-related osteonecrosis." (PMID 29703208, 2018). "Correspondingly, by suppressing PPARγ, several methods are employed to prevent steroid-related osteonecrosis." (PMID 29703208, 2018). "Previous studies have demonstrated that PPARγ is closely related to the induction of adipogenic differentiation and plays important roles in the development of steroid-related osteonecrosis." (PMID 29703208, 2018). "In summary, our data indicated that PPARγ inhibition by BADGE significantly decreases the incidence of osteonecrosis in steroid-treated rabbits." (PMID 29703208, 2018). "In this study, we investigated the preventive effects of PPARγ inhibition on steroid-related osteonecrosis in a rabbit model." (PMID 29703208, 2018). "Our results indicated that PPARγ inhibition prevented steroid-related osteonecrosis, and the effect was in part owing to reduced marrow fat infiltration." (PMID 29703208, 2018). "Furthermore, we explored the regulatory mechanism of continuous PPARγ expression, and we observed that osteonecrosis continued to progress after stopping the administration of GCs in SANFH." (PMID 35883192, 2022). "In conclusion, these observations demonstrated that pharmacological inhibition of PPARγ might represent an effective therapy for steroid-related osteonecrosis in the near future." (PMID 29703208, 2018). "Correspondingly, downregulation of PPARγ expression might induce osteogenic differentiation, reduce adipogenic differentiation, inhibit bone marrow adiposity, decrease intraosseous pressure, promote local blood perfusion and eventually prevent osteonecrosis." (PMID 29703208, 2018). "MiR-27a is downregulated and negatively correlated with PPARγ and gremlin 1 (GREM1) expression in steroid-induced osteonecrosis of femoral head patients." (PMID 34164391, 2021).
prediabetes (10 papers, 2012 to 2024). "There was a significant increase in the risk of developing prediabetes for both the rs1801282 polymorphism of the PPARG gene and the rs7903146 polymorphism of the TCF7L2 gene." (PMID 39767130, 2024). "Among the genes associated with lipid and carbohydrate metabolism disorders, a significant increase in the risk of developing prediabetes was observed for the rs1801282 polymorphism of the PPARG gene." (PMID 39767130, 2024). "The genetic polymorphisms of TCF7L2 and PPARG, explored in our investigation, assume global relevance due to the increasing prevalence of prediabetes and T2D on a global scale." (PMID 39451528, 2024). "Therefore, this study aims to investigate the genetic contribution of polymorphic variants of the TCF7L2 (rs7903146) and PPARG (rs1801282) genes to the risk of developing prediabetes in individuals of Kazakh ethnicity." (PMID 39767130, 2024). "The aim of this study was to assess the frequencies of two minor alleles of polymorphic variants in the TCF7L2 gene (rs7903146) and the PPARG gene (rs1801282), which are associated with the risk of prediabetes, in an ethnically homogeneous population of Kazakhs." (PMID 39451528, 2024). "By improving insulin sensitivity, PPARG helps maintain glucose homeostasis, an important factor in preventing the progression from prediabetes to T2DM." (PMID 39767130, 2024). "Numerous genes have been investigated concerning both T2DM and prediabetes, including PPARG (peroxisome proliferator-activated receptor gamma, rs1801282) and TCF7L2 (transcription factor 7-like 2, rs7903146)." (PMID 39767130, 2024). "This case-control study aimed to investigate the distribution of TCF7L2 (rs7903146) and PPARG (rs1801282) genotypes in cases with prediabetes and healthy controls of Kazakh ethnicity." (PMID 39767130, 2024). "Despite these limitations, this study emphasizes the significant role of TCF7L2 (rs7903146) and PPARG (rs1801282) in prediabetes, suggesting their potential as biomarkers, particularly among individuals of Kazakh ethnicity." (PMID 39767130, 2024). "H3K4me3 was enriched at the promoter of E2F1, LPL, SREBF2, SCD1, PPARG and IL6 in lean normoglycemic compared to morbid obese subjects with prediabetes." (PMID 30958852, 2019). "Several international studies have investigated the prevalence of PPARG (rs1801282) and TCF7L2 (rs7903146) genotypes in individuals with prediabetes belonging to different ethnicities with varying observations, but there is a lack of studies on the ethnic Kazakh population." (PMID 39767130, 2024).
tuberculosis (10 papers, 2012 to 2025). A chronic, recurrent infection caused by the bacterium Mycobacterium tuberculosis. "What is the main function of PPARγ in the formation of tuberculosis-associated FM?" (PMID 35432274, 2022). "In contrast, research on the role of PPARγ in tuberculosis has focused on its effect on lipid uptake." (PMID 35432274, 2022). "In the present study we provide evidence that PPARγ plays an important role in regulating lipid efflux in tuberculosis-related FM formation." (PMID 35432274, 2022). "Collectively, PPARγ is emerging as a regulator of tuberculosis pathogenesis and an attractive target for the development of adjunctive tuberculosis therapies." (PMID 22851964, 2012). "Network pharmacology, bioinformatics, and molecular docking as well as literature review revealed 13 compounds, including linoleic acid, abietic acid, and tretinoin, that might exert their anti-tuberculosis function via actions with PPARγ or MAPK pathway." (PMID 41155521, 2025). "Furthermore, future experimentation will be needed to prove that these antioxidants follow the PPARγ or MAPK pathway for tuberculosis inhibition." (PMID 41155521, 2025). "In all, the antioxidants from the bleeding sap of sponge gourd in treating TB is characterized by the combination of multi-components, multi-targets, and multi-pathways, among which the abietic acid, tretinoin, and linoleic acid might act with the PPARγ or MAPK pathway to inhibit tuberculosis." (PMID 41155521, 2025). "During tuberculosis, BLR49653 treatment had the same effect on CD36 expression and FM formation; in silicosis, PPARγ antagonist GW9662 treatment downregulated CD36 expression and inhibited FM formation." (PMID 35432274, 2022). "In contrast to earlier reports supporting a role for PPARγ in regulating CD36 expression during tuberculosis, our results could not demonstrate a significant involvement of PPARγ in HKMT-mediated modulation of CD36 expression." (PMID 38989454, 2024).
Abdominal obesity (9 papers, 2013 to 2025). Excessive fat around the stomach and abdomen. "Central obesity has been associated with the dysfunction of peroxisome proliferator-activated receptor-gamma (PPAR-γ), which is a regulator of fat storage and adipogenesis." (PMID 41007724, 2025). "Accordingly, the relative risk of abdominal obesity was increased 4.82 in subjects with higher concentration of PPARγ in compared with lower concentration of PPARγ after adjustment for age, sex and BMI (pvalue = 0.018, 95% CI from 1.30 to 17.75)." (PMID 24330836, 2013). "Analysis of the effect of PPARγ level on the relative risk of MetS components demonstrated the significant effect of circulating PPARγ on abdominal obesity." (PMID 24330836, 2013). "Additionally, individuals with central obesity, as indicated by higher WC, often exhibit elevated levels of peroxisome proliferator-activated receptor gamma (PPARγ) metabolites." (PMID 40260279, 2025).
adenoma (9 papers, 2012 to 2025). A neoplasm arising from the epithelium. "The two mutation-positive ≥4-cm adenomas had fusion PAX8/PPARG and mutant HRAS." (PMID 31780751, 2019). "Increasing evidence suggests that PPARγ activity is attenuated during the transition from adenoma to carcinoma, likely explaining why PPARγ agonists can block the early stages of tumorigenesis." (PMID 22848209, 2012). "The authors also found seven markers specifically able to differentiate between large adenomas and CRC (BCL3, PTGES, PPARG, MMP11, IL8, TNFSF13B, CXCR3)." (PMID 33806465, 2021).
allergic asthma (9 papers, 2007 to 2026). A asthma with a basis in a pathological type I hypersensitivity reaction. "Airway epithelial cells specific PPARγ could regulate airway inflammation and mucin expression in allergic asthma by functioning as a transcriptional repressor of MUC5AC, a major airway mucin gene." (PMID 39040099, 2024).
chronic myeloid leukemia (9 papers, 2015 to 2025). "Among the four small molecule drugs with the highest affinity for PPARG, bosulif has been reported in clinical trials for chronic myeloid leukemia." (PMID 36911676, 2023). "Exciting results for therapeutic effects of PPARγ activation have been obtained in chronic myeloid leukemia (CML)." (PMID 35954274, 2022). "Current trials of PPARγ agonists on chronic myeloid leukemia (CML) often act as a curative add-on to tyrosine kinase inhibitors, which are effective in refractory CML." (PMID 31614690, 2019).